LINC00908 (long independently transcribed non-coding RNA 908)
Synonyms: ASRPS; LINC01879; LINC00683
Gene: Long non-coding RNA gene on chromosome 18 (76,528,580 to 76,693,637, forward strand). Ensembl gene ENSG00000266256.
Diseases named in the same sentence as LINC00908 in open-access papers:
LINC00908 is named in the same sentence as 9 diseases in open-access papers, as found by Europe PMC text mining. Sharing a sentence is not in itself a finding about the gene and the disease. The quoted sentences say what the papers report.
prostate carcinoma (4 papers, 2020 to 2025). A carcinoma that arises from epithelial cells of the prostate gland. "This study aimed to explore the role of LINC00908 in prostate cancer (PCa) and its possible underlying mechanisms." (PMID 31938018, 2020). "Similarly, LINC00908 promotes the progression of prostate cancer and gastric cancer." (PMID 41384040, 2025).
breast carcinoma (3 papers, 2024). "ASRPS (encoded by LINC00908) acts as an antitumour peptide by reducing angiogenesis to significantly increase survival in patients with breast cancer." (PMID 38992718, 2024). "For example, in breast cancer, the LINC00908-encoded polypeptide ASRPS (a small regulatory peptide of STAT3), the lncRNA MAGI2-AS3-encoded polypeptide, and the lncRNA HCP5-encoded peptide have been proven to have functional roles in breast cancer pathogenesis." (PMID 39346726, 2024).
triple-negative breast carcinoma (3 papers, 2022 to 2024). An invasive breast carcinoma which is negative for expression of estrogen receptor (ER), progesterone receptor (PR), and human epidermal growth factor receptor 2 (HER2). "For example, a small peptide ASRPS with 60-aa encoded by LINC00908 functions as a potent anti-tumor polypeptide in triple-negative breast cancer by modulating STAT3 activity." (PMID 37285335, 2023).
colorectal cancer (1 paper, 2025). A primary or metastatic malignant neoplasm that affects the colon or rectum. "LINC00908 facilitates colorectal cancer cell proliferation via modulating the miR‐143‐3p/KLF5 axis." (PMID 40344383, 2025).
hepatocellular carcinoma (1 paper, 2025). A malignant tumor that arises from hepatocytes. "In particular, LINC00908 is responsible for hepatocellular carcinoma progression by increasing the stability of SOX‐4." (PMID 40344383, 2025).
tumor (5 papers, 2020 to 2025). "Overexpression of LINC00908 repressed PCa cell stemness and in vivo tumor growth, which indicated the tumor suppressive property of LINC00908 in PCa." (PMID 40344383, 2025). "We found that LINC00908 was low‐expressed in PCa cells, and it exerted suppressive functions in PCa cell stemness and tumor growth." (PMID 40344383, 2025). "ASRPS is a peptide of 60 amino acids encoded by LINC00908, which is down-regulated in triple-negative breast cancer (TNBC), and can inhibit angiogenesis and exert an anti-tumor effect in TNBC." (PMID 39030557, 2024). "In addition, in vivo experiments showed that overexpression of LINC00908 inhibited tumor growth of PCa." (PMID 31938018, 2020).
cancer (3 papers, 2020 to 2025). A tumor composed of atypical neoplastic, often pleomorphic cells that invade other tissues. "Current literature has demonstrated the regulatory function of LINC00908 in several human cancers." (PMID 40344383, 2025). "However, few researchers have studied the function of LINC00908 on cancer development." (PMID 31938018, 2020).
LINC00908 also shares sentences with these, for which no sentence is quoted: cervical cancer (1 paper); gastric cancer (1).